C3 (complement C3)
Diseases named in the same sentence as C3 in open-access papers (continued):
Sharing a sentence is not in itself a finding about the gene and the disease.
atypical hemolytic-uremic syndrome (28 papers, 2011 to 2026). A rare, genetic thrombotic microangiopathy due to dysregulation of the alternative complement pathway and characterized by the triad of hemolytic anemia, thrombocytopenia, and acute renal dysfunction. "There was a family history of atypical hemolytic uremic syndrome (aHUS) with a C3 gene mutation (p.I1157T) in his niece, who had several episodes of aHUS in her childhood." (PMID 37143613, 2023). "Heterozygous mutations in the C3 gene were described in patients with susceptibility to atypical hemolytic uremic syndrome (OMIM: 612925)." (PMID 36076978, 2022). "For example, while the association between C3 and C3 deficiency has “definitive” supportive evidence, C3-atypical hemolytic uremic syndrome association has “limited” supportive evidence; hence the value of the variant presented in this study." (PMID 33456446, 2020). "We here report on the first observation of a C3 mutation that is related to atypical hemolytic and uremic syndrome (aHUS), which occurred in a pancreatic islet transplant patient." (PMID 32950058, 2020). "Indeed, mutations in the C3 gene result in an abnormal protein, promoting complement overactivation and predisposing to renal injury (atypical hemolytic uremic syndrome) due to loss of regulation or direct overactivation of the C3 convertase." (PMID 30761135, 2019). "Additionally, because of the known genetic overlap between AMD and atypical hemolytic uremic syndrome (aHUS), we genotyped two recurrent aHUS-associated C3 mutations in the entire cohort." (PMID 24736606, 2014). "Atypical hemolytic uremic syndrome (aHUS) is a rare, life-threatening disease characterized by uncontrolled complement activation and is associated with various genetic factors, including multiple variants at the gene locus encoding the complement component 3 (C3)." (PMID 41674789, 2026). "Rare C3 gain of function (GoF) mutations may lead to atypical hemolytic uremic syndrome (aHUS)." (PMID 32064578, 2020). "The consumption and activation of C3 is a well-known marker for determining the activity of inflammatory diseases, such as rheumatic diseases or atypical hemolytic uremic syndrome." (PMID 34767613, 2021). "The low C3 levels and normal C4 levels along with positive complement H antibody titers strongly indicate the activation of the alternative pathway, thus suggesting a diagnosis of atypical hemolytic uremic syndrome (aHUS)." (PMID 39027763, 2024). "In atypical HUS (aHUS), deposition of complement factors C3 and C9 could be verified on the platelet membrane." (PMID 31402914, 2019). "In atypical hemolytic uremic syndrome activation of complement occurs on glomerular or microvascular endothelium causing a thrombotic microangiopathy; in most cases, no electron-dense deposits are seen on electron microscopy and glomerular C3 is not detected on immunofluorescence." (PMID 27460033, 2016). "Additionally, activation of the complement alternative pathway was detected on heme-exposed endothelial cells, resulting in C3 cell binding and MAC formation, a mechanism that contributes to endothelial damage and thrombosis in the atypical hemolytic uremic syndrome." (PMID 37373079, 2023).
geographic atrophy (28 papers, 2015 to 2026). "CFH, ARMS2/HTRA1 and C3 genes have been reported to increase the risk of progression from intermediate drusen to large drusen and from large drusen to geographic atrophy and neovascularization." (PMID 25893111, 2015). "The success of C3 inhibition in slowing geographic atrophy validates complement as a tissue-damaging amplifier in AMD and a tractable therapeutic target." (PMID 41394857, 2025). "Inhibition of complement component C3 slows the expansion of geographic atrophy, supporting the principle of lowering innate immune activity to preserve retinal tissue." (PMID 41394857, 2025). "Last year, the United States Food and Drug Administration (FDA) approved the first intravitreal injection therapy for geographic atrophy with the C3 inhibitor Pegcetacoplan." (PMID 39463155, 2024). "To date, there is still no commonly used treatment for dry AMD in daily clinical practice, although the complement C3 inhibitor pegcetacoplan has been recently reported to reduce the growth of geographic atrophy in patients with dry AMD." (PMID 37306515, 2023). "Complement inhibitors, particularly C3 and C5 inhibitors, have shown to be effective in slowing geographic atrophy in dry AMD, and numerous clinical trials are ongoing." (PMID 38073631, 2023). "Clinical trials targeting proteins encoded by the AMD-associated genomic loci C3, CFB, CFI, CFH, and ARMS2/HTRA1 are currently ongoing, and a phase III clinical trial for C3 inhibition recently showed a modest reduction of lesion growth in geographic atrophy." (PMID 36108770, 2022). "Since then, the field has rapidly expanded and even led to recent clinical trials to address geographic atrophy in AMD patients given the C3 inhibitor pegcetacoplan." (PMID 36077073, 2022). "Accordingly, anti-C3 and anti-C5 treatment are currently evaluated in late-stage clinical trials for geographic atrophy (GA) secondary to AMD71,72." (PMID 36371417, 2022). "Complex effects were observed in a phase 2 study using pegcetacoplan, which binds to C3 and consequently controls the cleavage of C3 for geographic atrophy (GA)." (PMID 36276919, 2022). "In a phase 2 trial, intravitreal injection of the C3 inhibitor Pegcetacoplan significantly reduced the geographic atrophy rate over 12 months." (PMID 34819935, 2021). "Correlation of C3 with AMD has led to clinical trial of C3 inhibitor in geographic atrophy patients, with reported positive results, however, a significant number of patients (~20%) converted to exudative AMD." (PMID 33362238, 2020). "Furthermore, clinical trial data show that inhibiting complement C3 (e.g. with pegcetacoplan) slows geographic atrophy progression, providing human proof-of-concept for targeting the innate complement pathway." (PMID 41394857, 2025). "Our analysis also showed increased expression of the complement component C3, which is strongly associated with AMD and has been shown to be interconnected with the expression of VEGF, RPE deterioration, geographic atrophy, and development of choroidal neovascularization." (PMID 36795578, 2023). "Based on these findings, it is interesting to speculate that perhaps FDA-approved C3 inhibitors (for geographic atrophy) such as Pegcetacoplan (SYFOVRE) may ultimately be repurposed for use in ML/DHRD, possibly with better functional outcomes than has occurred in dry AMD." (PMID 41198612, 2025). "In addition, phase 3 clinical data have confirmed the translational relevance of this pathway: the OAKS and DERBY trials showed that complement C3 inhibition with pegcetacoplan significantly slowed the progression of geographic atrophy secondary to AMD over 24 months." (PMID 41393127, 2025). "Just last year, pegcetacoplan (Syfovre), a C3 peptide inhibitor, was approved as one of only two FDA-approved drugs to minimize progression of geographic atrophy in AMD." (PMID 39114980, 2024).
geographic atrophy (continued). "It is also interesting that both anti-C3 and anti-C5 were given a label of ‘geographic atrophy’ despite the anti-C3 trials including both foveal and non-foveal involving lesions whilst in the anti-C5 trials, only non-foveal involving lesions were included." (PMID 39639153, 2025). "The C3 inhibitor pegcetacoplan and C5 inhibitor avacincaptad pegol has been FDA-approved as they are shown to significantly halt the atrophy progression in patients with geographic atrophy secondary to AMD." (PMID 39487449, 2024). "The C3 inhibitor Cp20 is a member of the compstatin family, which also includes the clinical therapeutic pegcetacoplan that is meanwhile approved for the treatment of PNH and geographic atrophy and the candidate drug AMY-101 (Cp40)." (PMID 37771595, 2023). "Previous work also reported C3 immunoreactivity for a subset of cone photoreceptors approximately 1.5 mm peripheral to geographic atrophy lesions but not in healthy retinas." (PMID 35784369, 2022). "Recently a complement C3 inhibitor and a C5 inhibitor have been FDA approved for the treatment of geographic atrophy but have not demonstrated improvement in visual function, have produced some serious adverse events and barely reduce the growth rate of the geographic atrophy." (PMID 38045700, 2023).
lymphopenia (28 papers, 2012 to 2025). Reduction in the number of lymphocytes. "C3 was also associated with an increased presence of neutrophils, and B and T cells lymphopenia based on transcriptomic and flow cytometry data." (PMID 37652913, 2023). "The factors that contribute to the state of hyperinflammation are persistent lymphopenia, neutrophilia, over-activation of complement components C3, C3a, C5, C5a and mannose binding lectin-associated serine protease (MASP2); in addition to the cytokine storm." (PMID 33708109, 2020). "Laboratory investigations showed lymphopenia, low C3 and C4 complement levels, positive antinuclear antibodies, anti-dsDNA antibodies, and anti-SSA/Ro antibodies." (PMID 37312164, 2023). "Increased IL6, lymphopenia, elevated neutrophils lasted longer in the fatal casea, who also had decreased C3." (PMID 33664741, 2021). "Fewer platelets, CD3 or CD4 counts, lower complement C3 level, lymphopenia, and elevated APTT, IL-6 or IL-10 also were related to the progression from oneset to death (all P < 0.05)." (PMID 32903644, 2020). "Immunopathology associated with lymphoproliferative cluster 2 specifically that additionally carried over to the lymphoproliferative cluster in total included CD4+ T cell lymphopenia (<419 cell/μL), high serum IgM (>334 mg/dL), and low C3 levels (<93 mg/dL)." (PMID 29375540, 2017). "Postpubescents showed significantly more renal involvement and lymphopenia, along with lower levels of C3 and C4, when compared with prepubescents." (PMID 22551316, 2012). "Specifically increased in males were lymphopenia, positive anti-Sm, direct Coombs, lupus anti-coagulant, low C3, and anti-dsDNA." (PMID 22690240, 2012). "Similarly, in another study, IL-10 is highly correlated with disease activity, SLEDAI, anti-dsDNA, C3, C4, and lymphopenia." (PMID 31697750, 2019). "The diagnosis of SLE was made according to the 2019 EULAR criteria, based on the combination of inflammatory polyarthralgia, lymphopenia, a high-titer ANA, the positivity of specific antibodies like anti-Sm and anti-dsDNA, and consumption of C3 and C4 complement fractions." (PMID 40852710, 2025). "Consistently with what was observed in human SARS-CoV patients, lymphopenia was observed in the lungs of both SARS-CoV MA15-infected C57BL/6J and C3–/– mice with reduced percentages of B cells and CD4 T cells relative to those in mock-infected mice following infection." (PMID 30301856, 2018). "The presence of lymphopenia, higher ANA titers, and positive anti-dsDNA antibodies was negative, whereas the presence of Hashimoto’s thyroiditis, a higher lymphocyte count, and a higher C3 level were positive predictors of the transition from active to latent EBV infection in a univariate analysis." (PMID 37047126, 2023).
paroxysmal nocturnal hemoglobinuria (28 papers, 2016 to 2025). Paroxysmal nocturnal hemoglobinuria (PNH) is an acquired clonal hematopoietic stem cell disorder characterized by corpuscular hemolytic anemia, bone marrow failure and frequent thrombotic events. "For example, in patients with paroxysmal nocturnal hemoglobinuria, C3 inhibition paradoxically led to increased C3 levels, likely due to reduced cleavage." (PMID 41347874, 2025). "A novel complement C3 inhibitor, pegcetacoplan, was recently approved to treat paroxysmal nocturnal hemoglobinuria, a condition commonly treated with complement C5 inhibitors." (PMID 40023814, 2025). "Pegcetacoplan, a C3 inhibitor, has shown effective and is approved for paroxysmal nocturnal hemoglobinuria (PNH)." (PMID 37795092, 2023). "Pegcetacoplan is used for the treatment of paroxysmal nocturnal hemoglobinuria, which is characterized by the destruction of red blood cells by complement component 3 (C3), part of the body’s innate immune system." (PMID 35164339, 2022). "For example, the most highly interconnected protein in the constructed network, C3, has been targeted using the long-acting C3 inhibitor, polyethylene glycol-Cp40, in paroxysmal nocturnal hemoglobinuria." (PMID 34741130, 2022). "Pegcetacoplan (C3 inhibitor) was recently approved by the FDA for paroxysmal nocturnal hemoglobinuria, in addition to avacopan (C5a receptor antagonist) for ANCA-associated vasculitis." (PMID 36211394, 2022). "The inhibition of activated complement has already demonstrated notable success in clinical practice, for example, C3 and/or C5 inhibitors for paroxysmal nocturnal hemoglobinuria (PNH) or targeting C1s in cold agglutination disease." (PMID 36291163, 2022). "After the recent successful approval of the C3 inhibitor pegcetacoplan for the treatment of paroxysmal nocturnal hemoglobinuria, iptacopan, a novel, low molecular weight, orally active, reversible, and selective inhibitor of Factor B (FB) of the complement AP, is currently developed." (PMID 39110227, 2024). "Recently, a specific C3 inhibitor, pegcetacoplan (Empaveli, Apellis Pharmaceuticals, Waltham, MA), was approved to treat paroxysmal nocturnal hemoglobinuria, and further studies should evaluate if C3 inhibitors can be used to dampen thromboinflammation triggered by air embolism." (PMID 35371063, 2022). "Pegcetacoplan is an anti-C3 agent that has been approved for the treatment of paroxysmal nocturnal hemoglobinuria (PNH)." (PMID 40731834, 2025). "Furthermore, research in C3 inhibition by pegcetacoplan (APL-2), a PEGylated C3 inhibitor, is ongoing in patients with paroxysmal nocturnal haemoglobinuria (PNH), a rare acquired life-threatening hematologic disease that causes complications through both haemolysis and thrombosis." (PMID 34830419, 2021). "In paroxysmal nocturnal hemoglobinuria (PNH), Cp40 blocked C3 fragment deposition and hemolysis in a dose-dependent manner, with near-complete inhibition at ~ 6 μM." (PMID 41187099, 2025). "In May 2021, pegcetacoplan was approved by the US FDA to treat adults with paroxysmal nocturnal hemoglobinuria (PNH), and it is the first to target C3, a complement component upstream of C5." (PMID 36671244, 2022). "More than 10% of patients with aAA may progress to develop clinically significant paroxysmal nocturnal hemoglobinuria (PNH), a rare and life-threatening disease due to the activation of plasma complement (C3)." (PMID 38892889, 2024). "APL-2 (pegcetacoplan) is a compstatin derivative that prevents C3 activation and has recently been approved by the FDA for the treatment of paroxysmal nocturnal hemoglobinuria (PNH)." (PMID 34682837, 2021).
ischemic stroke (27 papers, 2013 to 2025). A stroke disorder caused by obstruction of blood flow to the brain, due to thrombotic (local blood clot formation) or embolic (due to a blood clot or other material traveling from another site) event. "Clinically elevated serum C3 levels in ischemic stroke patients were linked to poorer outcomes at three months after ischemia, suggesting C3 as a potential prognostic biomarker." (PMID 41342963, 2025). "A significant increase in serum C3 levels in patients with ischemic stroke has been linked to poor clinical outcomes." (PMID 38789486, 2024). "C3-deficient (C3 −/−) mice show a substantial drop in infiltrative neutrophils and oxidative stress levels after an ischemic stroke, which diminishes brain damage and improves neurological and functional results." (PMID 39649720, 2024). "In the acute stage of ischemic stroke, increased levels of C3 signaling through C3aR1 are associated with worsening pathology and can lead to the development of epilepsy." (PMID 38035266, 2023). "In a mouse model of transient ischemic stroke, C3 deficiency via the genetic knock-out method reduced brain infarct volume and neutrophil influx following 1 day of ischemic stroke but impaired subsequent neurogenesis after 7 to 28 days of brain ischemia." (PMID 31011487, 2019). "The data presented here support the notion of a dual role for complement in ischemic stroke by comparing C3 deficiency with transient approaches of complement inhibition using CR2-Crry and CR2-fH." (PMID 26714866, 2015). "Among these proteins, complement C3 is associated with inflammation and ischemia/reperfusion injury and with poor outcomes after ischemic stroke, which may increase its risk within 3 months." (PMID 36959823, 2023). "In addition, genetic variation in the C3 gene was found to be associated with ischemic stroke, particularly with cryptogenic stroke." (PMID 31011487, 2019). "In addition, genetic variation in the C3 gene was found to be associated with ischemic stroke, in particular with the cryptogenic stroke subtype." (PMID 23977229, 2013). "Meanwhile, elevated serum component C3 levels increased risks of adverse clinical outcomes after ischemic stroke, and C3 depletion attenuated brain edema and neutrophil infiltration around the clot after ICH." (PMID 36891553, 2023). "A previous study reported that neuroinflammation induced C3-positive reactive astrocytes and ischemic stroke activated S100A10-positive reactive astrocytes." (PMID 38188669, 2023). "C3 is a central complement pathway protein that increases in the brain following ischemic stroke peaking 3 days after onset." (PMID 37270727, 2023). "In ischemic stroke, complement component 3 (C3) is critical in the complement cascade and immune recognition 7-9." (PMID 34373737, 2021). "We observed that C1s assists in the activation of C3 and was upregulated in ischemic stroke patients." (PMID 32466277, 2020). "We found that C3 expression increased in the peri-atrophic region and ipsilateral hippocampus of old mice compared to the young peri-atrophic region and ipsilateral hippocampus at the chronic stage of ischemic stroke injury." (PMID 40661422, 2025). "Interestingly, a previous clinical study reported that the serum complement C3 concentration is a valuable prognostic biomarker of ischaemic stroke." (PMID 38532579, 2024). "Taken together, C1s may be highly expressed in ischemic stroke patients to activate the complement system following ischemic stroke, which would act to restore brain injury by promoting C3 activation." (PMID 32466277, 2020). "C3 was increased in the brain after ischemic stroke, and inhibiting C3 activity could attenuate ischemic brain injury." (PMID 31011487, 2019). "Similarly, a recent study focusing on young ischemic stroke patients (18-50 years) also showed that the level of C3 in plasma was related to the prognosis 3 months after ischemic stroke." (PMID 31011487, 2019).